BAP1 (BRCA1 associated deubiquitinase 1)
Diseases named in the same sentence as BAP1 in open-access papers (continued):
Sharing a sentence is not in itself a finding about the gene and the disease.
mesothelioma (continued). "Of the few studies on targeted drugs that include mesothelioma, most late-stage studies are focused on BAP1 mutations while inactivating NF2 mutations (and other hippo pathway mutations) are more prevalent in pleural mesothelioma patients." (PMID 34621176, 2021). "Germline mutations in BAP1 result in a cancer syndrome involving the development of BAP1-mutated melanocytic skin tumors and a high incidence of mesothelioma." (PMID 33262459, 2021). "Previous genomic analyses of mesothelioma have shown a mutational landscape dominated by loss of function mutations in BAP1 and NF24,5." (PMID 34580349, 2021). "Nevertheless, to date, relatively limited data exist on the co-occurrence of melanoma and/or mesothelioma with renal neoplasia and germline associations with BAP1 and MITF p.E318K alterations." (PMID 34767027, 2021). "This genetic association study assesses the co-occurrence of melanoma and/or mesothelioma with renal neoplasia, and germline associations with BAP1 and MITF p.E318K alterations in patients who underwent nephrectomy." (PMID 34767027, 2021). "Another case series highlighted a family presenting with multiple mesotheliomas and melanocytic tumors found to have an inherited germline BAP1 mutation (c.1948T>A (p.Tyr646*); two of the family members developed meningiomas in addition to their mesotheliomas." (PMID 34504799, 2021). "BAP1 loss is therefore reliable as a “rule in” for mesothelioma, but pleural malignancy cannot be excluded in its absence." (PMID 34209209, 2021). "BAP1 alterations occur in one mutant allele and are inherited as autosomal dominant mutations: a study of germline-mutated mesothelioma showed 43.1% of relatives carried the same mutation of their probands." (PMID 34249695, 2021). "Offering additional explanation for this low diagnostic sensitivity, 30–40% of mesotheliomas have been shown to carry a wild-type BAP1 and therefore stain positively in a similar manner to benign lesions." (PMID 34209209, 2021). "Loss of BAP1 is implicated in a distinct subset of cancers like development of mesothelioma, uveal and cutaneous melanoma, clear cell renal cell carcinoma and bladder cancer." (PMID 34591877, 2021). "BAP1 is an important tumor suppressor, and germline BAP1 mutations in human result in a strong predisposition to a range of cancers, including mesothelioma, uveal melanoma, renal cell carcinoma, and others." (PMID 33912157, 2021). "The discovery that germline BAP1 mutations cause mesothelioma and other malignancies, namely, uveal cancer, meningioma, and melanoma, overall defined as “BAP1-related cancer syndrome”, elucidated some of the key pathogenic mechanisms." (PMID 33802313, 2021). "Heterogeneity was evident, with potential explanations including different cut-off values for BAP1 loss, inclusion of participants with pleural and peritoneal mesothelioma and variation in diagnostic accuracy across mesothelioma histological subtypes." (PMID 34209209, 2021). "Enhancer of zeste homolog 2 (EZH2) is upregulated in mesothelioma, and preclinical models have identified a possible association between BAP1 loss and EZH2 upregulation." (PMID 33802313, 2021). "More recently, the loss of immunohistochemical expression of BAP1 has been suggested to strongly support the diagnosis of mesothelioma in women presenting with abdominal disease." (PMID 34068638, 2021). "One year after BAP1 genotyping, mutation-specific follow-up allowed an early diagnosis of mesothelioma in the proband." (PMID 32325837, 2020). "For mesothelioma, the top genes with mutations were BAP1 (BRCA-associated protein 1), NF2 (neurofibromin 2), and SETD2 (SET domain containing 2, histone lysine methyltransferase)." (PMID 32033319, 2020). "In BAP1-TPDS, inactivating germline BAP1 mutations cause development of mesothelioma, melanoma, and other neoplasms." (PMID 33105797, 2020).
mesothelioma (continued). "Germline mutations in BAP1 are associated with tumor predisposition syndrome for mesotheliomas and melanocytic tumors, whereas deletions and point mutations have been identified in lung and breast cancers." (PMID 32549302, 2020). "Analysis of BAP1-TPDS patients has revealed an association between mesothelioma development and BAP1 mutations." (PMID 33105797, 2020). "The integrative multiomics analysis of mesothelioma TCGA data revealed that the activation of type 1 IFN has been linked to the status of BRCA-associated protein 1 (BAP1), a gene which is frequently mutated in mesothelioma." (PMID 33050791, 2020). "A germ-line mutation in BAP1 is thought to cause a syndrome that includes mesothelioma, uveal and cutaneous melanoma as well as other neoplasms." (PMID 32392897, 2020). "For example, BAP1-mutated mesothelioma is significantly correlated with female predominance, younger age at onset, epithelioid differentiation, and better prognosis." (PMID 33585209, 2020). "Germline BAP1 mutations cause a tumor syndrome composed of mesothelioma, cutaneous and uveal melanomas, meningioma, and renal cell carcinoma, amongst others." (PMID 33346248, 2020). "BAP1 germline variants predispose individuals to high risks of development of aggressive cancers, such as, uveal melanoma, mesothelioma, cutaneous melanoma and renal cell carcinoma at a younger age with poor prognosis." (PMID 33240524, 2020). "Germline BAP1 mutations are associated withthe development of several tumors including renal cell carcinoma, mesothelioma,uveal melanoma, and various other malignancies." (PMID 32422649, 2020). "The nuclear localization of BAP1 is essential to its function, with the loss of nuclear localization observed in many cancers including uveal melanoma, mesothelioma and ccRCC11,13,32–35." (PMID 33240524, 2020). "This is however, unfortunately complicated by the fact that the loss of BAP1 is uncommon in the sarcomatoid and desmoplastic forms of mesothelioma." (PMID 33014860, 2020). "Since 2011, over 600 articles have evaluated the role of BAP1 mutations in mesothelioma and in other cancers." (PMID 33065998, 2020). "Here, we report a novel pathogenic BAP1 germline variant in a family with a history of BIMTs, cutaneous melanomas, and mesotheliomas." (PMID 31706282, 2019). "Heritable mutations in the BAP1 tumour suppressor gene predispose individuals to mesothelioma and other forms of cancer." (PMID 30967648, 2019). "We had access to the Haematoxylin and Eosin (H&E) stain for three of these supra-carcinoids, on which the pathologists discarded misclassifications with LCNEC, SCLC, or mesothelioma in the case of the asbestos-exposed BAP1-mutated sample." (PMID 31431620, 2019). "BAP1 germline mutation predisposes carriers to the development of mesothelioma, uveal, and cutaneous melanoma and various other tumors, a condition known as BAP1 cancer syndrome." (PMID 31641107, 2019). "Mutations and deletions determining BAP1 loss have been described in several tumors including lung, breast, melanoma, and mesothelioma." (PMID 31766522, 2019). "Previous studies in mesotheliomas have revealed that over 60% of mesotheliomas harbor BRCA1 associated protein 1 (BAP1) inactivating mutation or copy number loss, making BAP1 the most commonly altered gene in this malignancy." (PMID 30777124, 2019). "The ratio of peritoneal to pleural mesothelioma is significantly higher in carriers of germline BAP1 mutations compared to the rate in the sporadic mesotheliomas." (PMID 30001711, 2018). "For example, in our patient with BAP1 associated mesothelioma, monitoring for recurrence was accomplished using MRI rather than CT scans to reduce the risk of radiation-induced cancers." (PMID 30001711, 2018). "But first, the next step would be to conduct a clinical trial of TRAIL in patients with mesothelioma and assess if those with tumours that have mutations in the gene for BAP1 do indeed respond better." (PMID 29345617, 2018).
mesothelioma (continued). "Recently, the BAP1 mutation and its involvement in cancer survival have been reported in a range of tumor types, including uveal melanoma, mesothelioma, renal cancers, and biliary tract cancers." (PMID 30395583, 2018). "We studied BAP1, ASXL2, and UBE2Es expression in 10 human malignant mesothelioma biopsies containing wild-type BAP1 and in 10 human mesothelioma biopsies containing mutated BAP1, as determined in previous studies." (PMID 30349006, 2018). "Loss of BAP1 function is implicated in the oncogenesis of several types of cancers including uveal, mucosal and some cutaneous melanomas in humans, as well as in mesothelioma." (PMID 30060843, 2018). "Germline mutations in the BRCA-1 associated tumor protein 1 (BAP1) increase susceptibility to mesothelioma and other cancers." (PMID 30001711, 2018). "The challenge is to identify these cases of mesotheliomas because when mesothelioma and other cancers develop in carriers of germline BAP1 mutations, they often have a better prognosis." (PMID 30001711, 2018). "Clinical data have shown that BAP1 gene is frequently mutated in various tumors, including mesothelioma and melanoma." (PMID 30013160, 2018). "Htz germline mutations in BAP1 predispose to a range of benign and malignant tumours, including mesothelioma." (PMID 30060470, 2018). "Germline mutations in the BAP1 gene are one of the most significant factors that lead to the development of mesothelioma." (PMID 30060501, 2018). "It has been estimated that only about 1% of mesotheliomas are associated with germline BAP1 mutations." (PMID 30001711, 2018). "Of these, 109 coding mutations (70%) were identified in both sequencing platforms and included the known mesothelioma driver gene, BAP1, while 20 mutations (13%) and 27 mutations (17%) were only called in the BGISEQ-500 and HiSeq X Ten data respectively." (PMID 29320538, 2018). "Loss of functional BAP1 leads to TRAIL sensitivity in early passage mesothelioma cell lines, human tumour explants and mouse xenograft models." (PMID 29345617, 2018). "In the laboratory, mesothelioma cells that have mutations in the gene that codes for a protein known as BRCA associated protein-1 (or BAP1 for short) were killed much more effectively by a drug known as TNF-related apoptosis-inducing ligand (TRAIL)." (PMID 29345617, 2018). "For instance, heterozygous mice with one wild type and one null BAP1 allele develop mesothelioma at much lower levels of exposure to asbestos than wild-type animals." (PMID 30258054, 2018). "Germline mutations in BAP1 have been described in families with a hereditary increase in the risk of uveal melanoma, cutaneous melanoma, mesothelioma, Merkel cell carcinoma, and several other cancers." (PMID 29166932, 2017). "Germline mutations in BAP1 are associated with several familiar cancers, among which are lung adenocarcinoma, meningioma, mesothelioma, CM, and UM." (PMID 28229253, 2017). "Somatic and germline mutations of BAP1 results in metastasizing uveal melanoma and mesothelioma, and a syndrome characterized by uveal, cutaneous melanoma and mesothelioma, respectively." (PMID 28812986, 2017). "Recently, several studies have identified somatic and germline BAP1 mutations in a wide-range of cancers, including mesothelioma, uveal melanoma, lung adenocarcinoma, renal cell carcinoma, meningioma, and melanocytic neoplasms." (PMID 29088836, 2017). "The BAP1 gene also carries rare germline mutations in families with a high incidence of several types of cancers, such as mesothelioma, uveal melanoma, lung adenocarcinoma, melanocytic neoplasms, and renal cell carcinoma." (PMID 29088836, 2017). "BRCA1-Associated-Protein 1 (BAP1) is a dynamic tumor suppressor which, when mutated, has been associated with an increased risk of uveal melanoma, cutaneous melanoma, mesothelioma, and several other cancers." (PMID 29166932, 2017).
mesothelioma (continued). "More recently, sporadic somatic BAP1 mutations have been shown to occur in the setting of both mesothelioma and uveal melanoma." (PMID 29166932, 2017). "Annual screening for uveal melanoma, mesothelioma, and renal cancer should be considered for carriers of BAP1 germline mutations." (PMID 28283772, 2017). "In view of the recently described BAP1 associated cancer syndrome manifesting melanomas and mesotheliomas, we tested the risk of mesothelioma when cutaneous melanomas were diagnosed in FDRs." (PMID 28198461, 2017). "BAP1 mutation carriers should also be explicitly warned about asbestos exposures, given their predisposition toward mesothelioma." (PMID 28283772, 2017). "It is also possible that differential gene alterations (such as loss or mutation of NF2 or BAP1) can also contribute to metabolic changes and altered mitochondrial morphologies in mesothelioma and should be more thoroughly investigated." (PMID 27080907, 2016). "A tumor suppressor gene most commonly deleted or mutated in mesotheliomas (∼60% of cases) is BRCA1 associated protein-1 (BAP1), a C-terminal family of deubiquitinating enzymes (DUBs) linked to DNA damage repair regulation." (PMID 28191281, 2016). "This possibility is further supported by the recently reported inverse correlation between strong EZH2 expression and the loss of the chromatin modifier BAP-1, whose increasingly deregulated nature in sporadic mesotheliomas we are currently investigating." (PMID 27705913, 2016). "Apart from domestic, environmental, and occupational exposure to asbestos or other carcinogenic mineral fibers, mesotheliomas can also be caused by inherited BAP1 germline mutations." (PMID 28191281, 2016). "More recently, mutations in the BAP1 tumor suppressor gene have been observed in 20-25% of mesothelioma tumor samples." (PMID 25952750, 2015). "BAP1 is a tumor suppressor gene and mutations have been identified in around 40 families with accumulation of UM, CM, mesothelioma, RCC, and basal cell carcinoma (BCC)." (PMID 25803691, 2015). "We analysed 5 families with CM and mesothelioma, and found truncating BAP1 mutations in 2 of the families." (PMID 25803691, 2015). "Recent studies have identified germline mutations in the gene encoding BRCA1 associated protein-1 (BAP1) which can predispose to mesothelioma." (PMID 26202904, 2015). "Up to 80% of mesothelioma are directly attributable to asbestos exposure and it was recently shown that mice with heterozygous germline BAP1 knockout were predisposed to develop mesothelioma upon asbestos exposure." (PMID 25970771, 2015). "Germline BAP1 mutations were first described in mesothelioma families with no heavy exposure to carcinogens which are known to cause a high incidence of mesothelioma." (PMID 26202904, 2015). "Previous studies of BAP1 have shown that BAP1 loss promotes colony-forming ability of mesothelioma cells, and that re-expression of BAP1 in BAP1-deficient markedly decreases colony-formation." (PMID 25952750, 2015). "Germline BAP1 mutation carriers are thought to be highly susceptible to mesothelioma even at modest levels of asbestos exposure that would be considerably less tumorigenic in the general population." (PMID 26202904, 2015). "In fact, somatic BAP1 mutation occurs in only around 1% of lung adenocarcinoma, but is far more prevalent in uveal melanoma, mesothelioma and renal clear cell carcinoma." (PMID 25970771, 2015). "Mesothelioma occurring in germline BAP1 mutation carriers have been reported to be less aggressive clinically and associated with prolonged survival compared with sporadic mesothelioma." (PMID 26202904, 2015). "We believe these models would also enable further studies into functional aspects of BAP1, which is mutated in nearly a quarter of all mesotheliomas." (PMID 25952750, 2015). "Individuals with a BAP1-germline mutation have an increased risk to develop cutaneous and ocular melanoma and mesothelioma, apart from the risk to develop multiple MBAITs." (PMID 25593912, 2014).
mesothelioma (continued). "Germline BAP1 mutations confer susceptibility to uveal melanoma, epithelioid atypical Spitz tumors, cutaneous melanoma, and mesothelioma." (PMID 25536104, 2014). "While frequent somatic BAP1 mutations have been found in mesothelioma, uveal melanoma and cutaneous melanoma response, we report the first finding of BAP1 mutation in HCC." (PMID 25159915, 2014). "Somatic BAP1 mutations are infrequent but have been reported in prostate, ovarian, colon, breast, lung cancers and in mesothelioma." (PMID 25536104, 2014). "In a follow up report, Wiesner and colleagues identified a third family with a BAP1 mutation that co-segregated with mesothelioma and also showed evidence of a melanocytic lesion in a mutation carrier." (PMID 23977234, 2013). "Dominant mutations in the BAP1 (BRCA1-associated protein 1) gene were recently reported to cause a new, rare cancer-prone syndrome that renders the individual susceptible to mesothelioma and melanoma, among others." (PMID 23626673, 2013). "They found two different frameshift mutations in BAP1 responsible for the elevated risk of mesothelioma in these individuals." (PMID 23977234, 2013). "Three of their four patients with uveal melanoma and BAP1 mutations subsequently developed mesothelioma." (PMID 22613358, 2012). "Mutations in BAP1 are infrequent in the general population but high in mesothelioma (20.1%) and uveal melanoma (44.1%)." (PMID 22613358, 2012). "However, in vivo studies have documented that germline Bap1 heterozygous mice are highly susceptible to mesothelioma upon exposure to even minimal amounts of asbestos fibers." (PMID 40867321, 2025). "However, given the wide credible intervals and the 95% credible interval, we cannot conclude that a germline Bap1 heterozygous mutation in mice is associated with an increased incidence of mesothelioma." (PMID 40867321, 2025). "In mice, there is limited data and controversy about whether germline Bap1 heterozygous mutations alone cause mesothelioma." (PMID 40867321, 2025). "BAP1 loss detected by IHC helps to distinguish mesothelioma from other malignancies." (PMID 40361508, 2025). "Termed low‐grade BAP1‐associated mesothelioma (L‐BAM), this indolent subtype may benefit from conservative management distinct from that of aggressive sporadic disease." (PMID 40904706, 2025). "Thus, we cannot conclude that germline Bap1 heterozygous mice have an increased risk of spontaneous mesothelioma compared to WT mice." (PMID 40867321, 2025). "In addition, we investigated spontaneous mesothelioma development in a heterozygous Bap1 mouse model with a different knockout mutation generated by another research group, also in the C57BL/6 background." (PMID 40867321, 2025). "Individuals carrying a germline BAP1 mutation are at increased risk of developing mesothelioma." (PMID 40867321, 2025). "In mice, there is limited information and controversy regarding whether germline Bap1 heterozygous mutations alone cause mesothelioma, despite these mice being highly susceptible to even minimal asbestos exposure." (PMID 40867321, 2025). "Carriers of a pathogenic BAP1 mutation are at high risk for the development of benign BAP1-inactivated melanocytic tumors and various cancers, including mesothelioma, uveal and cutaneous melanomas, renal cell cancer, basal cell carcinoma, meningioma, and cholangiocarcinoma." (PMID 40867321, 2025). "Germline pathogenic mutations in BAP1 result in an autosomal dominant tumor predisposition syndrome, increasing the risk for uveal melanoma, mesothelioma, and renal cell carcinoma—predominantly clear cell—and at a younger median age compared to sporadic occurrences." (PMID 41440218, 2025). "Mesotheliomas exhibit extensive aneuploidy and are driven by copy number alterations affecting a restricted number of tumour suppressors, which include loss of 3p21 (harbouring BAP1) and 9p21 (CDKN2A)." (PMID 39168966, 2024).